CD40 (CD40 molecule)
Diseases named in the same sentence as CD40 in open-access papers (continued):
Sharing a sentence is not in itself a finding about the gene and the disease.
tumor (continued). "IL-2/CD40 reduced CD25 and IFN-γ in tumor-associated CD4+ T cells in both age groups alongside reductions in the regulatory markers CD73 and CTLA-4." (PMID 30560130, 2018). "Thirty‐nine percent of mice treated with anti‐PD‐1, anti‐CTLA4 and an agonist CD40 antibody had long‐term complete tumor remission and prolonged survival." (PMID 30003190, 2018). "Another CD40L-mutant, Ad5/3-hTERT-E1A-hCD40L (also named CGTG-401) with replication controlled by the hTERT promoter, selectively killed CD40-expressing cancer cells resulting in tumour regression and apoptosis in CD40-expressing xenograft models." (PMID 29904022, 2018). "As a result, expression of CD39, A2AR, A2BR, ICOS and LAG-3 was higher on tumor-associated CD8+ T cells from young, compared to elderly, IL-2/CD40-treated mice." (PMID 30560130, 2018). "In a mouse model of pancreatic cancer, treatment with a CD40 agonist increases sensitivity of the tumor to gemcitabine via depletion of fibrosis by monocytes/macrophages." (PMID 30483271, 2018). "Inhibition of macrophages in elderly mice improved the response to IL-2/anti-CD40 immunotherapy leading to a reduction in tumor growth and improved survival (78%)." (PMID 30459812, 2018). "More recent studies suggested that CD40 agonists can mediate both T-cell-independent and T-cell-dependent immune mechanisms of tumor regression in pancreatic cancer." (PMID 29385739, 2018). "Recently, utilizing an anti-CD40 antibody to elicit immunization against HPVE6/E7 successfully primed CD8 T cells to kill papillomavirus-related tumor cells in vitro." (PMID 29464051, 2018). "Poorer CTL responses in elderly mice is likely to contribute to their reduced tumor responses to IL-2/CD40-treatment." (PMID 30560130, 2018). "We also examined responses to treatment with intra-tumoral IL-2/anti-CD40 antibody immunotherapy and found it was less effective in elderly (38% tumor regression) compared to young mice (90% regression)." (PMID 30459812, 2018). "Peritumoral injection of a slow-release formulation containing an agonistic anti-CD40 antibody was tested in preclinical tumor models and this treatment resulted in systemic tumor-specific CTL expansion and eradication of distant tumors." (PMID 30619273, 2018). "This was demonstrated using experimental tumor models with multiple tumors, where the anti-tumor effect was severely impaired when CD40 activating therapy was administered at a site distant from the tumor." (PMID 27714433, 2017). "In both types, it is expected that antitumor efficacy highly depends on the CD40 status of the tumor infiltrate, mainly tumor-specific CTLs and possibly TAMs." (PMID 29387053, 2017). "Combination of anti-CD40 with IL-2 has been shown to induce delayed growth and regression across several murine tumor models." (PMID 28428882, 2017). "This CD40L/CD40 interaction leads to the maturation of DCs, stimulates T helper 1(Th1)-type immune responses and promotes T cell activation and migration into the tumor microenvironment." (PMID 28427434, 2017). "CD40 agonists bind the CD40 molecule on antigen-presenting cells and activate them to prime tumor-specific CD8+ T cell responses." (PMID 29129918, 2017). "Use of agonist CD40 mAbs with high-affinity fosters activation of APCs (DCs, monocytes, and B cells), leading to stimulation of tumor-specific immune responses." (PMID 28970830, 2017). "Recently, it was reported in a mouse tumor model that use of agonist CD40 mAb reversed resistance to PD-1, downregulating PD-1 levels in T cells via IL-12 production." (PMID 28970830, 2017). "ISF35 also inhibited tumor growth and prolonged mouse survival significantly better than the intratumoral-injected agonist CD40 mAb (P = 0.028, unpaired t test)." (PMID 29129918, 2017). "In the current study, DCs were stimulated with agonistic anti-CD40 mAbs after tumor-antigen loading and were inoculated s.c. into mice that were irradiated and reconstituted with ex vivo—expanded CD4+ T cells." (PMID 28854279, 2017).
tumor (continued). "Activation of CD40 on DC improves their cross-presentation of tumor antigens and release of IL-12, thereby boosting the number of activated tumor-directed T effector cells." (PMID 27714433, 2017). "Agonistic anti-CD40 can synergise with chemotherapy and cure advanced tumours in mice, especially when administered after chemotherapy." (PMID 28619093, 2017). "In APC, the CD40:CD40L reverse stimulatory immune checkpoint is associated with proliferation of MC, MØ, BC, SMC, and tumor cells, and inflammatory molecular production." (PMID 28738836, 2017). "A short duration of DC stimulation with agonistic anti-CD40 mAbs in vitro can enhance the migration of DCs to draining LNs and the ability of DCs to present tumor antigens to tumor-specific T cells." (PMID 28854279, 2017). "Many tumor cells express CD40, including almost 100% of B-cell malignancies and up to 70% of solid tumors, including melanoma." (PMID 29129918, 2017). "These B cells supposedly induce protumorigenic activity of macrophages or directly interact with tumor cells by CD40/CD154 signaling pathway." (PMID 29050338, 2017). "It has also been shown that increased affinity of the CD40 agonistic antibody results in increased accumulation of the antibody in the tumor area." (PMID 27714433, 2017). "A recent report showed that anti-CD40 treatment induces PD-L1 up-regulation on tumor-infiltrating monocytes and macrophages, which was strictly dependent on T cells and IFN-γ." (PMID 26942414, 2017). "Extensive preclinical studies of anti-CD40 therapy have shown efficacy in various tumour model systems, and several clinical agents targeting the CD40 signalling axis have been or are currently under investigation." (PMID 28619093, 2017). "Blockade of MHC class I, CD40 or CD80 resulted in a substantial reduction of anti-tumor cytotoxicity against target tumor cells, although it was dependent on cell type." (PMID 27671170, 2016). "To determine how treatment with anti-CD40 mAb, sunitinib or the combination affects the prevalence of cytotoxic T-cells within the tumor tissue, we performed immunostaining for the cytotoxic T-cell marker CD8 in B16.F10 and T241 tumor sections." (PMID 27385210, 2016). "Combining anti-CD40 mAb therapy with sunitinib significantly inhibited tumor growth and increased survival." (PMID 27385210, 2016). "We sought to examine how this cell population is affected by the combined anti-CD40 mAb and sunitinib therapy in the tumor and peripheral lymphoid tissue." (PMID 27385210, 2016). "Our results suggest that combining anti-CD40 mAb therapy with sunitinib treatment can synergistically increase expression of endothelial adhesion molecules in tumor vessels that have a repressed expression of these molecules due to VEGF stimulation." (PMID 27385210, 2016). "Tumor supernatant from PV-10-treated cells led to DC maturation, with the up-regulation of surface CD40." (PMID 27177220, 2016). "Important to note is that CD40 triggering in malignant cells is able to promote tumor cell proliferation leading to tumor progression." (PMID 27656185, 2016). "It has been shown that short-term CD40 signaling augments DC migration to tumor-draining LNs and induced protective immunity." (PMID 27177220, 2016). "Compared with CD4+ T cell help, anti-CD40 induced an even stronger bias towards IgG2a/c, and protected against lung metastases after i.v. administration of B16.mHELMCC tumor cells." (PMID 27121060, 2016). "The CD40 aptamer blockade which is expressed in several B-cell malignancies reduces tumor growth and augments mice survival by 30%." (PMID 27413756, 2016). "In other studies, immunization of mice with anti-CD40 mAb chemically coupled to tumor idiotype resulted in significantly retarded tumor growth." (PMID 27827885, 2016). "To determine if either anti-CD40 or sunitinib treatment affected vessel function, we injected biotin-labeled lectin and Hypoxyprobe-1 (pimonidazole hydrochloride) in B16.F10 tumor-bearing mice." (PMID 27385210, 2016).
tumor (continued). "Given the fact that activating CD40 signaling would promote CD40-expressing tumor progression, we managed to generate a CD40 agonistic aptamer conjugated with a shRNA aimed at inhibiting NMD." (PMID 27413756, 2016). "Anti-CD40 mAb treatment increased the percentage of CD11b+Gr1+ cells in the tumor draining lymph node in both the B16.F10 and T241 model, but co-treatment with sunitinib reversed the effect." (PMID 27385210, 2016). "Blocking of the MHC class I and CD80 resulted in a substantial reduction of IFN-γ production against all target tumor cells, but CD40 blockade significantly reduced only in A549 tumor cells." (PMID 27671170, 2016). "Before loading with tumour lysate, DCs were characterized by flow cytometry to analyse the expression of MHC class I and II molecules, costimulatory molecules (CD86, CD80, CD40), and markers associated with maturation (CD83, CCR7, PD-L1)." (PMID 26795765, 2016). "We have previously shown that a local low-dose of anti-CD40 mAb is superior to systemic treatment, and that four days of sunitinib treatment is sufficient to induce chemokine expression in B16.F10 tumor endothelial cells." (PMID 27385210, 2016). "We previously reported that simultaneously stimulating CD3 on T cells and CD40 on B cells augments the antitumor reactivity of tumor-draining lymph node (TDLN) cells." (PMID 27528023, 2016). "CD40 in conjunction with TLR-4 has been reported in substantially augmenting DCs activity to regress tumor growth and optimally activate T cells." (PMID 27729911, 2016). "The combination of i.v. tumor plus anti-CD40 stimulated a large increase in HEL-specific serum IgG2a/c, with smaller increases in IgG1, IgG3, IgA and IgE and no change in IgG2b or IgM." (PMID 27121060, 2016). "The expression of ICAM-1 and VCAM-1 adhesion molecules was up-regulated on tumor endothelial cells only when anti-CD40 mAb treatment was combined with sunitinib." (PMID 27385210, 2016). "Agonistic anti-CD40 antibody represents a new class of immunotherapeutic drugs, inducing T-cell activation through licencing of DCs in the tumor microenvironment and in the tumor draining lymph nodes." (PMID 27385210, 2016). "Vaccination with the peptide epitope TB10.44−11 (TB10), anti-CD40 mAb and poly(I:C), a vaccination strategy used in multiple infection and tumor models, generates a large number of TB10-specific memory CD8+ T cells in C57BL/6 mice." (PMID 26745507, 2016). "Treatment with either anti-CD40 mAb or sunitinib alone had a moderate effect on B16.F10 tumors, while the combination of anti-CD40 mAb therapy and sunitinib substantially decreased tumor growth." (PMID 27385210, 2016). "The combination of an agonist CD40 antibody with gemcitabine chemotherapy showed tumor regression in both PDAC patient and genetically engineered PDAC mouse model." (PMID 27655706, 2016). "A combination of a monoclonal antibody (CP-870,893) against CD40 with gemcitabine induced a measurable anti-tumor immune response." (PMID 26266422, 2015). "This study aimed to investigate the effects of anti-CD40-induced E-cadherin + DCs on the T cell response and antitumour activity in the tumour microenvironment." (PMID 25651850, 2015). "In this study, we report significant CD40 upregulation in tumor-infiltrating MDSC when compared with splenic MDSC." (PMID 26462153, 2015). "There are recent reports regarding CD40 expression on several kinds of tumor cells; however, its role in tumor cells is not clearly known." (PMID 25992978, 2015). "CD40 agonists mediate tumor cell death and in combination with DC activation anti-tumor immune responses." (PMID 26500646, 2015). "Tumour volume decreased, and the survival time of tumour-bearing mice was prolonged significantly following the injection of CD40-mediated inflammatory E-cadherin+ DCs compared with injection of E-cadherin− DCs." (PMID 25651850, 2015).
tumor (continued). "Many subsets of DCs exist in the agonistic CD40 antibody-mediated tumour microenvironment or under sterile inflammatory response conditions." (PMID 25651850, 2015). "As a functional consequence of this newly identified mechanism and of other potential actions by CD40, tumor growth was significantly suppressed in CD40 KO mice when compared with WT mice." (PMID 26462153, 2015). "In tumor, inhibition of PD-1 effectively augmented CD40+, CD80+, CD86+ cells, and especially significantly increased MHC-II+ DCs." (PMID 26573233, 2015). "Beatty and coworkers found that CD40 agonists alter tumor stroma and show efficacy against pancreatic carcinoma in mice and humans." (PMID 26101781, 2015). "On the other hand, CD40 ligation has positive consequences on tumor growth, survival and resistance to chemotherapy and metastatic potential." (PMID 25763299, 2015). "To confirm CD40 expression in LGSC tumor cells, we immunostained matching sections from all eight SBOTs and five LGSCs." (PMID 26313915, 2015). "Anti-DR5 induces apoptosis of TNF-related apoptosis-inducing ligand- (TRAIL-) sensitive tumor cells, whereas anti-CD40 activates DCs and anti-CD137 costimulates T cells, to induce tumor-specific immunity." (PMID 25961061, 2015). "We have shown that CD40-mediated inflammatory E-cadherin + DCs enhance T cell responses in tumour immunity in vitro." (PMID 25651850, 2015). "Further analysis indicated that the CD40+% of tumor-infiltrating MDSC in WT mice ( 68.58 ± 7.35) was significantly higher than the CD40−% (31.52 ± 7.18; p < 0.01)." (PMID 26462153, 2015). "CD40-mediated inflammatory E-cadherin + DCs therefore possess an excellent antitumour ability via enhancement of the anti-tumour T cell response and suppression of Treg cell development." (PMID 25651850, 2015). "CD40, expressed on antigen-presenting cells, mediates tumor-specific priming and expansion of T lymphocytes." (PMID 26266422, 2015). "Specifically, peritoneal macrophages from mice treated with anti-CD40 antibody and CpG were able to inhibit tumour cell proliferation in vitro and suggested a potential role in vivo in an antigen-dependent manner." (PMID 24969320, 2014). "In our studies, targeting agonist anti-CD40 antibody (Ab) into the tumor bed generated important local changes." (PMID 24955376, 2014). "The interaction between the CD40-CD40 ligand has been demonstrated to regulate immune responses, and CD40 has an important effect on promoting tumor cell apoptosis or tumor growth." (PMID 25009656, 2014). "In tumor-prone transgenic mice, CD40-mediated neovascularization was essential for early-stage tumorigenesis." (PMID 24745825, 2014). "The ligation of CD40 on the surface of tumor cells inhibits the growth of tumor and induces apoptosis." (PMID 25108500, 2014). "CD40 was preferentially expressed on tumor-infiltrating MDSCs at the early phase of progression, but was gradually downregulated with tumor progression." (PMID 25009656, 2014). "We have previously demonstrated that immunotherapy combining agonistic anti-CD40 and IL-2 (IT) results in synergistic anti-tumor effects." (PMID 25119341, 2014). "Residual tumor outgrowth following debulk plus anti-CD40 was delayed by 2–3 days compared to debulk alone." (PMID 25518732, 2014). "The tumors were found to induce MDSC accumulation, and the MDSCs exhibited different levels of CD40 expression with tumor progression." (PMID 25009656, 2014). "We show that the post-surgical environment can be significantly altered by the co-administration of adjuvant IMQ and anti-CD40, resulting in strong, systemic anti-tumor activity." (PMID 25518732, 2014). "Further analysis revealed that the MDSC levels were found to positively correlate with tumor progression and that CD40 expression levels inversely correlate with the accumulation of MDSCs." (PMID 25009656, 2014).
tumor (continued). "Aldara-based TCI efficiency can be increased by costimulatory signals like CD40 ligation or UV-B irradiation leading to enhanced memory formation and improved tumor protection." (PMID 25025233, 2014). "We reckon that tumor cells inhibit T lymphocytes activation by expressing CD40 mutants to escape from immune monitoring." (PMID 24885116, 2014). "Subsequent reports have suggested that in many cancers, CD40 activation by its ligand results in a completely reverse situation, i.e., enhancement of tumor growth and progression." (PMID 25117071, 2014). "In this study, IMQ and anti-CD40 were chosen specifically for their ability to promote tumor-specific CD8 T cell egress from the draining lymph nodes and their likely role in improving CD8 entry/function at the effector site." (PMID 25518732, 2014). "Several studies including ours have shown that agonist anti-CD40 Ab is a potent tumor microenvironment modifier." (PMID 24955376, 2014). "The recent finding that anti-CD40 therapy can induce anti-tumor activity in mice and humans independently of T cells but presumably via activating macrophages has revived the role of macrophages in anti-tumor responses." (PMID 24612598, 2014). "Enhance production of IL-6, IL-8, TNF-α, and GM-CSF and corresponding caspase activation can contribute to CD40-dependent tumor growth inhibition." (PMID 25117071, 2014). "Along the same line, macrophage-dependent tumor cytotoxicity via nitric oxide can be stimulated by IL-2/anti-CD40 immunotherapy." (PMID 24723924, 2014). "Flow cytometric analysis of the harvested tumor lysate-loaded DCs revealed a phenotype characteristic of mature DCs with high expression of CD40, CD80, CD83, CD86, HLA-ABC, HLA-DR, and CCR7." (PMID 25694811, 2014). "In their approach, an anti-CD40 antibody is dissolved in a slow release formulation of the adjuvant Montanide and injected near the tumor site." (PMID 24741998, 2014). "By targeting CD40, the antibody promoted tumour cell apoptosis, activated DC and macrophage activation and maturation." (PMID 24969320, 2014). "To increase the tumor selectivity of CD40 agonist-based therapies, we developed an approach in which soluble trimeric CD40L (sCD40L) is genetically fused to tumor targeting antibody fragments, yielding scFv:CD40L fusion proteins." (PMID 24741998, 2014). "The results showed a significant increase in the percentage of CD40+ MDSCs in the tumor-bearing mice compared with the tumor-free mice." (PMID 25009656, 2014). "This study further confirmed the requirement for the combination of IL-2 or IL-15 with anti-CD40 mAb for tumor regression versus the partial effects seen with anti-CD40 mAb treatment alone in large tumor burdens." (PMID 24955376, 2014). "In animal models, antagonistic antibodies against IL-4 or agonistic anti-CD40 favor anti-tumor Th1 functions." (PMID 23577028, 2013). "Immune stimulatory molecules, such as 41-BB, CD40, and OX-40, are also targets, and early-phase clinical trials of activating antibodies to these have shown that they can mediate tumor regression." (PMID 24216706, 2013). "Collectively, these data along with the finding of sCD137 mRNA induction in CLL B cells by CD40 stimulation suggest that CD137 expression should be induced in tumor cells in the body, resulting in elevated levels of sCD137 in CLL patients." (PMID 23696891, 2013). "CD40 agonists are suggested to mediate both T cell-dependent and T cell-independent immune mechanisms of tumor regression in mice and humans." (PMID 24303367, 2013). "After exposure to LF-MF, the percentage of CD40+ DC was significantly increased in both normal mice and tumor-bearing mice, from 0.72% to 1.19%, and from 1.25% to 1.98%, respectively." (PMID 24314291, 2013). "For the clinical use of agonistic CD40 therapeutics it is imperative to achieve higher tumor selectivity to ensure an acceptable toxicity profile." (PMID 23840967, 2013).